PDE9A (phosphodiesterase 9A)
Diseases named in the same sentence as PDE9A in open-access papers (continued):
Sharing a sentence is not in itself a finding about the gene and the disease.
colon carcinoma (1 paper, 2021). "R2 database and TCGA colon cancer patients data from UCSC Xena also ensured the positive correlation between PDE9A and CEACAM7." (PMID 34016083, 2021). "PDE9A contributes consolidated pathways (platelet homeostasis mediated) with MAPK14 which can carry out an important role in colon cancer prognosis." (PMID 34016083, 2021). "Statistical analysis from this database revealed that the expression of PDE9A is significantly attenuated in colon cancer samples compared with the normal counterparts." (PMID 34016083, 2021). "We used different databases namely Gent2, PrognoScan, GEPIA, UALCAN, OncoLnc, and R2 to analyze the survival plot or Kaplan-Meier plot for the PDE9A gene against colon cancer." (PMID 34016083, 2021). "Thus, this study suggests that high expression of the PDE9A gene is positively correlated with a good prognosis in colon cancer patients." (PMID 34016083, 2021). "This interaction may lead to PDE9A high expression to a higher survival rate for colon cancer patients." (PMID 34016083, 2021). "Besides, the Log-rank test curve also depicted that a higher survival rate was detected with high levels of PDE9A expression in colon cancer patients." (PMID 34016083, 2021). "Furthermore, the correlation analysis between PDE9A expression and DNA methylation heat map in the TCGA colon cancer sample types depicted that PDE9A expression positively related to PDE9A promoter methylation at some CpG sites (blank frame)." (PMID 34016083, 2021). "The PDE9A promoter methylation had been analyzed in colon cancer tissues." (PMID 34016083, 2021). "Furthermore, we correlated PDE9A gene expression and DNA methylation heat map in TCGA colon cancer sample types by adopting the UCSC Xena database." (PMID 34016083, 2021). "To ensure this positive co-expression pattern between PDE9A and CEACAM7, we also look into TCGA colon cancer patient data via UCSC Xena." (PMID 34016083, 2021). "The Kaplan–Meier curves disclosed that high expression of the PDE9A gene was related to encouraging conditions in OS (overall survival), RFS (relapse-free survival), and DSS (disease-specific survival) in colon cancer patients." (PMID 34016083, 2021).
depression (1 paper, 2021). "GRIK4 and PDE9A contribute to critical pathways involved in depression and antidepressant response, including glutamatergic signalling, neuroplasticity and neurogenesis." (PMID 33589590, 2021).
diabetes (1 paper, 2022). "PDE9A is an intracellular cyclic guanosine monophosphate (cGMP) hydrolase, which has been exploited as one of the most promising therapeutics for treatment of metabolic diseases, such as diabetes and Alzheimer’s, as well as fatigue syndromes." (PMID 36313119, 2022).
Down syndrome (1 paper, 2025). "The overexpression of HSA21 genes like DYRK1A, PDE9A, PCP4, and PCNT in Down syndrome disrupts calcium homeostasis, primarily by suppressing the calcineurin pathway." (PMID 41274866, 2025).
dystrophin deficiency (1 paper, 2016). "The aggregate results from our study imply that treatment of neurobehavioral symptoms associated with developmental disturbances stemming from dystrophin deficiency and impaired cGMP signaling in the cerebellum may be improved by using either a PDE9A specific inhibitor or a PDE5A inhibitor." (PMID 27676442, 2016).
ischemic stroke (1 paper, 2025). A stroke disorder caused by obstruction of blood flow to the brain, due to thrombotic (local blood clot formation) or embolic (due to a blood clot or other material traveling from another site) event. "cGMP and cAMP signaling is essential in regulating the diameter of the cerebral artery, and the activation of PDE9A is associated with neurovascular migraine and ischemic stroke." (PMID 40440257, 2025).
prostate carcinoma (1 paper, 2019). A carcinoma that arises from epithelial cells of the prostate gland. "Our data confirmed that the treatment of prostate cancer cells with ENZA enhances the effect of radiation through down-regulation of NKX3-1, ZMIZ1, SPDEF and PDE9A genes and up-regulation of LAT, PTPRN2 and OSBPL10 genes in LNCaP cells, as well as up-regulation of CYP1B1 genes in C4-2 cells." (PMID 31221986, 2019).
pulmonary hypertension (1 paper, 2025). Increased pressure within the pulmonary circulation due to lung or heart disorder. "For example, in a murine model of chronic hypoxia-induced pulmonary hypertension (a right-ventricular pressure-overload model), Pde9a deletion did not alter RV hypertrophy or cGMP signaling." (PMID 40650137, 2025).
rectal cancer (1 paper, 2021). A primary or metastatic malignant neoplasm that affects the rectum. "PDE9A demonstrated the highest positive correlation for rectal cancer recurrence with a marker gene CEACAM7." (PMID 34016083, 2021).
squamous cell carcinoma (1 paper, 2023). A carcinoma arising from squamous epithelial cells. "PDE9A is a specific cGMP and HIST1H2BG is a histone and has shown potential as a biomarker for the early diagnosis and subsequent diagnosis of squamous cell carcinoma." (PMID 37446311, 2023).
type 1 diabetes mellitus (1 paper, 2019). A chronic condition characterized by minimal or absent production of insulin by the pancreas. "LAT as a gene involved in KEGG immune and inflammatory pathways, whereas PTPRN2 and PDE9A were previously shown to be associated with type I diabetes mellitus pathway and purine metabolism, respectively." (PMID 31221986, 2019).
ulcerative colitis (1 paper, 2021). An inflammatory bowel disease involving the mucosal surface of the large intestine and rectum. "In summary, this study shows the protective effect of a PDE9A inhibitor in ulcerative colitis by suppressing oxidative stress and inflammation as well as reversing the Treg/Th17 cells imbalance." (PMID 33967779, 2021).
tumor (5 papers, 2013 to 2025). "It was found that the promoter methylation level of PDE9A in sample types, individual cancer stages, patient race, patient gender, patient age, patient weight, tumor histology, and T53 mutation status was reduced than normal tissues." (PMID 34016083, 2021). "Overall, the prognostic value of PDE9A gene could be used as a potential tumor biomarker for CRC." (PMID 34016083, 2021). "Reduced expression of the mRNAs for the ADCY5, EVX1, GFRA1 and PDE9A genes was significantly correlated with clinicopathological parameters, indicating that DNA methylation alterations, even from the precancerous stage, ultimately determine the tumor phenotype through gene silencing." (PMID 23544068, 2013). "The relatedness between PDE9A mRNA expression levels and different tumor stages of COAD was also evaluated, where PDE9A is significantly downregulated in stage II." (PMID 34016083, 2021). "Thus, PDE9A might have a potential function as a prognostic biomarker or tumor marker." (PMID 34016083, 2021). "DNA hypermethylation of the ADCY5, EVX1, GFRA1, PDE9A, and TBX20 genes resulted in reduced mRNA expression in tumorous tissue samples." (PMID 23544068, 2013). "PDE9A decreases PKG activity through the hydrolysis of cGMP, whereas the stimulation of cGMP/PKG signaling can suppress Wnt/β-catenin transcription, inhibit the proliferation of cancer cells, and enhance tumor immunity." (PMID 41163195, 2025). "Interestingly, when PDE9A, CADM3, and FNBP1 were used as co-predictors, they all showed low expression in tumor tissue, suggesting their potential use as biomarkers for predicting CRC." (PMID 37446311, 2023). "Among them, ACAA1, GART, PDE9A, RPL3, TUBA1A, and TUBG1 gene products interact with several proteins known to be involved in the PRAD pathway and particularly important for apoptosis inhibition and tumor growth." (PMID 33712625, 2021).
cancer (2 papers, 2021 to 2025). A tumor composed of atypical neoplastic, often pleomorphic cells that invade other tissues. "Research has demonstrated that PDE9A is implicated in the pathogenesis of various tumors and cancers and can selectively hydrolyze cyclic guanosine monophosphate (cGMP)." (PMID 41163195, 2025). "The expression pattern of PDE9A is associated with diverse tumors and carcinomas." (PMID 34016083, 2021). "Systematic mRNA expression analysis carried out here from multiple databases was enough to prove that PDE9A expression across a wide range of cancer types in which it is significantly downregulated in CRC." (PMID 34016083, 2021). "To identify a co-ordinated expression mediated cancer prognosis of PDE9A, we employed the co-expression profile via UALCAN website." (PMID 34016083, 2021). "Using the differential analysis tool of the Oncomine database, we analyzed cDNA microarray data for PDE9A in 20 different human cancer types." (PMID 34016083, 2021). "The expression of PDE9A was also estimated by the GENT2 database where results are depicted in boxplot across 72 paired cancer vs. normal tissues." (PMID 34016083, 2021). "Here, we have utilized several bioinformatics databases including Oncomine, UALCAN, GEPIA, GENT2, R2, OncoLnc, PrognoScan, cBioportal, UCSC Xena, GeneCards, GeneMania, and STRING to detect the role of PDE9A in cancer prognosis and progression." (PMID 34016083, 2021). "For analyzing the expression of PDE9A in various cancers, we compared its transcriptional levels in various cancer tissues with their corresponding normal tissues by adopting various databases like Oncomine, GEPIA, Gent2, UALCAN, GeneCard." (PMID 34016083, 2021). "These predicted interacting genes of PDE9A may be involved in the regulation of cancer progression and prognosis." (PMID 34016083, 2021). "Hence, the results implied that the status of methylation in the PDE9A DNA promoter region can be related to PDE9A expression in cancer tissues." (PMID 34016083, 2021). "In addition, PPIs and co-expression analysis demonstrated that PDE9A shares interaction networks with other genes that had a promising role in cancer pathology and may act as a potential biomarker or prognostic marker." (PMID 34016083, 2021). "Therefore, PDE9A could be a prospective candidate as a therapeutic target in different types of carcinoma." (PMID 34016083, 2021). "Currently, while there are clinical drugs targeting PDE9A, including BAY-7081 and PF-04447943, their application in cancer treatment remains unexplored." (PMID 41163195, 2025).
cardiovascular disease (2 papers, 2022 to 2025). "By the mid-2010s, these landmark findings—from the enzyme’s molecular characterization to its unique regulation of the NO-independent NP–cGMP pathway in failing hearts—established PDE9A as a promising therapeutic target for cardiovascular diseases." (PMID 40650137, 2025). "The early findings thus pointed to PDE9A as a novel therapeutic target in cardiovascular disease, distinct from the well-known PDE5A, by suggesting that blocking PDE9A could augment NP/cGMP signaling and mitigate cardiac stress responses." (PMID 40650137, 2025).
bacterial infection (1 paper, 2022). "Based on their average logistic regression coefficients, the five most important genes for bacterial classification were CEPT (+), RPGRIP1 (-), FCER1A (-), IFI27 (-), and PDE9A (-), where plus indicates upregulation and minus indicates downregulation for bacterial infection." (PMID 35184750, 2022).
neurodegenerative disease (1 paper, 2022). A disorder of the central nervous system characterized by gradual and progressive loss of neural tissue and neurologic function. "The results of previous studies suggesting that PDE9A inhibition can improve neurodegenerative diseases may need to be reconsidered with the knowledge of this new finding." (PMID 35968392, 2022).
PDE9A also shares sentences with these, for which no sentence is quoted: cognitive) diseases (2 papers); Huntington disease (2); trisomy 21 (2); acute myeloid leukemia (1); Anxiety (1); brain disease (1); cecum adenocarcinoma (1); cholangiocarcinoma (1); clear-cell renal cell carcinoma (1); colon adenocarcinoma (1); colon adenoma (1); colon mucinous adenocarcinoma (1); colorectal adenoma (1); dilated cardiomyopathy (1); endothelial dysfunction (1); glioblastoma (1); hypertrophy (1); kidney cancer (1); leiomyoma (1); leiomyosarcoma (1); metabolic disease (1); neurological diseases (1); Obesity (1); Parkinson disease (1); psychiatric disorder (1); Rectal Adenocarcinoma (1); Rectal Mucinous Adenocarcinoma (1); stomach cancers (1); thyroid cancer (1); tongue cancer (1).
A further 1 disease shares a sentence with PDE9A in 1 paper.